GAPDH (glyceraldehyde-3-phosphate dehydrogenase)
Diseases named in the same sentence as GAPDH in open-access papers (continued):
Sharing a sentence is not in itself a finding about the gene and the disease.
prostate carcinoma (28 papers, 2006 to 2025). A carcinoma that arises from epithelial cells of the prostate gland. "We determined the expression pattern of six HERV transcripts in cDNA derived from primary prostate epithelial cells and three primary and two immortalised prostate cancer cell lines using qPCR, standardising expression relative to the housekeeping gene GAPDH." (PMID 33802118, 2021). "PTBP3 was increased in prostate cancer cell lines compared to skin fibroblasts with GAPDH as the reference gene." (PMID 30634466, 2019). "To verify the role of myosin 1C isoform A mRNA expression as a putative prostate cancer marker we performed RT qPCR normalized by three reference genes (GAPDH, YWHAZ, HPRT1) on PC3, RWPE-1, LNCaP and 22Rv1 cell lines." (PMID 30498638, 2018). "A high percentage, 90.5% to 100%, sorted cells from the CWR-R1 prostate cancer cell line demonstrated expression of GAPDH and actin genes in our preliminary experiments." (PMID 27785389, 2016). "Examples of good reference human genes include; ACTB and GAPDH in prostate cancer; GAPDH and YWHAZ in idiopathic pregnancy-derived placenta; and HPRT1 and SDHA in sepsis." (PMID 26406496, 2015). "In a study on the biosynthesis of GAPDH in prostate cancer, the presence of five isozymes of GAPDH in human malignant cells were reported while only four were detected in normal prostate tissue." (PMID 21073742, 2010). "However, GAPDH is associated with several functions during evolution such as membrane fusion, microtubule bundling, phosphotransferase activity, nuclear RNA export, DNA replication and repair, apoptosis, age-related neurodegenerative disease, prostate cancer and viral pathogenesis." (PMID 18325098, 2008). "GAPDH transcription was increased in hypoxia in particular, and since it correlated in prostate cancer cell lines with the upregulation of hypoxia-inducible factor-1α protein levels, GAPDH was considered particularly unfavorable as an endogenous control gene in hypoxic conditions." (PMID 40943534, 2025). "GAPDH could enhance the transcriptional activity of AR in prostate cancer cells, and PPIB could regulate cell-cycle related genes including CCDC74A which further promotes cell proliferation." (PMID 37729607, 2023). "In addition, it has been observed that the GAPDH was up-regulated in rat hepatomas, malignant murine cell lines and human prostate carcinoma." (PMID 16515701, 2006). "Using castration-resistant prostate cancer cells, miR-644a was found to be a potent tumor suppressor that can inhibit glycolytic activity and the expression of the key glycolytic enzyme glyceraldehyde 3-phosphate dehydrogenase (GAPDH) in vitro and in xenograft models." (PMID 40126351, 2025). "Considering prostate cancer cell types, ACTB/GAPDH and ACTB/HPRT1 are the most suitable reference gene combinations for mRNA analysis, and miR-16/miR-1228-3p and RNU6-2/RNU43 for miRNA analysis in AR+, and AR− and normal cell lines, respectively." (PMID 29386530, 2018). "Each QD was conjugated to oligonucleotides complementary to either GAPDH (QD608), PTEN (QD693), or A20 (QD800) mRNA and were then mixed and applied simultaneously to LNCaP prostate cancer cells using the 1-step QD-FISH protocol." (PMID 30367061, 2018). "Considering prostate cancer cell types, ACTB /GAPDH and ACTB/HPRT1 are suggested to be the most suitable reference gene combinations for mRNA analysis." (PMID 29386530, 2018). "We not only analysed the expression levels of CFTR in HT-29 cells, HIF-1α in HEK-293T cells, GAPDH in liver tissue of mouse, and serum AFP in HCC patients, but also the glycosylation changes in the sera of prostate cancer patients, in combination with the optimised fixation method." (PMID 31040299, 2019). "Using a set of three reference genes (YWHAZ, GAPDH, and HPRT1), we analyzed myosin 1C isoform A mRNA expression in a set of cancer and non-cancer cell lines and confirmed the specificity of its expression in prostate cancer cells." (PMID 30498638, 2018).
prostate carcinoma (continued). "Additional cell lines, including a human prostate cancer cell line (PC-3), immortalized mouse aortic endothelial cells (iMAEC) and monkey kidney fibroblast (COS-7) cells were transfected with Cy3-labeled VEGF, KDR and GAPDH siRNAs by SW treatment." (PMID 26243452, 2015). "Moreover, circATP2C1 expression in prostate cancer cells did not change significantly after RNase R treatment, whereas mRNA expressions of linear ATP2C1 and GAPDH were significantly reduced." (PMID 41228362, 2025).
lung adenocarcinoma (24 papers, 2007 to 2025). A carcinoma that arises from the lung and is characterized by the presence of malignant glandular epithelial cells. "Furthermore, in the study of lung adenocarcinoma, bioinformatics analysis has revealed GAPDH as a prognostic marker associated with ferroptosis, whose expression level correlates with the tumor’s immune microenvironment." (PMID 39744129, 2024). "This is particularly evident in lung adenocarcinoma and squamous cell carcinoma, where GAPDH expression shows the strongest correlation with the m6A reader protein IGF2BP1." (PMID 38928396, 2024). "Using GAPDH as the exemplar, we incorporated five tools—hTFtarget, ENCODE, ChIP_Atlas, GTRD, and KnockTF—alongside correlation analysis with TCGA lung adenocarcinoma and GTEx lung tissue data (correlation coefficient threshold: 0.3)." (PMID 39062464, 2024). "Hyaluronate-modified α-Cyclodextrin nanoparticles inhibit GAPDH gene with a silencing efficiency of 55% using 1000 nM of siRNA in human lung adenocarcinoma cells." (PMID 35631507, 2022). "Our analysis of TCGA database showed that expression of the tryptophan transporter, solute carrier 7A5 (SLC7A5) is significantly upregulated in lung adenocarcinoma compared with normal controls and positively correlates with expression of glycolytic enzyme GAPDH." (PMID 37095081, 2023). "Finally, by integrating the results of PPI network analysis and one-way COX regression analysis, we identified six RBPs that are both DEGs and associated with lung adenocarcinoma prognosis—IGF2BP3, SNRPE, GAPDH, MRPL12, MRPL15, and INTS8, with IGF2BP3 being the most differentially expressed." (PMID 40801655, 2025). "The candidate proteins GAPDH and RAC1 showed the highest connectivity with other differentially expressed proteins between the lung adenocarcinoma group and the healthy group using STRING." (PMID 36404333, 2022). "Densitometry analysis of the Western blot bands also revealed that native Bcl-xL protein levels in normal NP-69 cells were significantly lower than both lung adenocarcinoma cells lines, A549 and SK-LU1 upon normalization against GAPDH." (PMID 24339958, 2013). "Integrated analyses of RNA-seq and ChIP-seq to access BACH1 targets using lung adenocarcinoma identified that BACH1 activates transcription of hexokinase 2 (HK2) and Glyceraldehyde 3-phosphate dehydrogenase (GAPDH) at their promoters as a transcriptional activator." (PMID 33809182, 2021). "A549 lung adenocarcinoma cells were transfected with non-target siRNA, GAPDH siRNA, and four different siCEACAM6 sequences." (PMID 31474761, 2019). "Combining immunotherapy with strategies targeting GAPDH to induce ferroptosis in lung adenocarcinoma may offer a novel therapeutic approach." (PMID 39744129, 2024).
gastric cancer (22 papers, 2007 to 2025). A primary or metastatic malignant neoplasm involving the stomach. "In our study, the GAPDH gene was used as the reference gene applied to the AGS gastric cancer cell line." (PMID 37895364, 2023). "We examined the levels of KLK1–8 mRNAs compared with GAPDH mRNA in various gastric cancer cell lines using RT-PCR." (PMID 27863404, 2016). "Extracellular GAPDH, or its N-terminal domain, inhibited gastric cancer cell growth, a finding confirmed in other cell systems." (PMID 25785838, 2015). "While IL-6 stimulated the growth and survival of almost all gastric cancer cell lines used here, GAPDH suppressed the growth of MKN-7 and MKN-28 cells." (PMID 25785838, 2015). "We firstly examined GAS5 expression level in 89 paired gastric cancer samples and adjacent, histological normal tissues by qRT-PCR, and normalized to GAPDH." (PMID 24884417, 2014). "The level of HOTAIR expression was determined in 78 paired gastric cancer samples and adjacent, histologically normal tissues by qRT-PCR, and normalized to GAPDH." (PMID 24775712, 2014). "The human gastric cancer tissues were further classified according to the HOTAIR expression level into the High-HOTAIR group (HOTAIR / GAPDH >1.0) and Low-HOTAIR group (HOTAIR /GAPDH < 1.0)." (PMID 24130837, 2013). "With 'stomach cancer cell lines', the rankings from two analyses were identical, i.e. GAPDH-B2M was the most stable reference gene combination followed by RPL29." (PMID 20507635, 2010). "The RQs by B2M, GAPDH as single reference gene and B2M-GAPDH that were predicted to be the most optimal combination of reference genes for 'stomach cancer cell lines' by geNorm showed similar high-low patterns." (PMID 20507635, 2010). "ACTB and GAPDH showed most abundant expression in both 'stomach cancer cell lines' and 'non-stomach cancer cell lines', but in contrast HPRT1 showed lowest expression level." (PMID 20507635, 2010). "In the case of 'non-stomach cancer cell lines', addition of GAPDH as the third gene to the two optimally expected genes B2M-RPL29 increases by 0.0218 of the stability value M, with its pair-wise variance V2/3 of 0.032." (PMID 20507635, 2010). "For example, the most unstable gene, HPRT1, in 'stomach cancer cell lines' has much wider range of expression compared to GAPDH or B2M." (PMID 20507635, 2010). "CXCR4 mRNA was determined by real-time reverse-transcription PCR in 34 gastric cancers, and its expression in each specimen was standardized to GAPDH expression." (PMID 20699000, 2010). "Using GAPDH-B2M combination for comparing gene expressions in 'stomach cancer cell lines' and RPL29-B2M combination for comparing in 'all stomach tissues' is therefore recommended." (PMID 20507635, 2010). "The GAPDH expression was successfully detected from all of gastric cancer cell lines." (PMID 35017627, 2022). "While the level of pT606‐Kaiso was decreased in most gastric cancer samples, the ratio of pT606‐Kaiso to total Kaiso was positively and significantly associated with the amounts of CDH1 (adjusted by GAPDH) in gastric cancer and the paired normal tissue samples from 12 patients." (PMID 35851744, 2022). "Besides, we evaluated the gene expression of GAPDH of GCM-isolated single gastric cancer cell lines (n = 12) for the quality control (QC) for single-cell RNA-seq analysis." (PMID 35017627, 2022). "The amount of secreted GAPDH was higher in Hs738 cells than gastric cancer cell lines." (PMID 25785838, 2015). "In addition, the mRNA levels of TFF2/GAPDH in gastric cancer tissues were significantly lower than those in the corresponding non-neoplastic mucosal tissues (mean ± SE, 3.4±2.7 vs. 9.6±5.4, respectively; P=0.046)." (PMID 24765170, 2014). "In addition we suggest that GAPDH-B2M combination for normalizing expression in 'stomach cancer cell lines' and RPL29-B2M combination for comparison between normal and tumor in 'all stomach tissues'." (PMID 20507635, 2010).
gastric cancer (continued). "Our results indicated that the convergent primers could amplify both circCNIH4 and GAPDH using cDNA and genomic DNA (gDNA) templates from gastric cancer cells (MKN-74 and HGC-27), while the divergent primers could only amplify circCNIH4 using cDNA as template rather than gDNA template." (PMID 34364402, 2021). "Furthermore to investigated the correlation between DC-SIGNR and HNRNPKP2, the two genes expression were verified by qRT-PCR in 17 paired formalin fixed and paraffin embedded gastric cancer tissues and corresponding para-carcinoma tissues, normalizing to GAPDH." (PMID 28403883, 2017). "In advanced gastric cancer (pathologic stages III and IV) patients, the post-operative expression levels of PPL/GAPDH, miR140-5p/miR197, and miR301a/miR197 were significantly increased compared with the pre-operative levels." (PMID 40429589, 2025). "The literature confirmed that 18S had good linearity and stability compared with the reference genes glyceraldehyde 3-phosphate dehydrogenase, U6 small nuclear RNA (U6), β-actin (ACTB), and tubulin (TUB) in gastric cancer." (PMID 34222007, 2021). "Taken together, our results showed that gastric stromal cells positively regulated the growth of gastric cancer cells through the PGE2-TNFα-IL-6 paracrine pathway, but negatively through secreted GAPDH that bound to E-cadherin." (PMID 25785838, 2015). "MKN-45 and MKN-74 cells expressed E-cadherin weakly compared to other gastric cancer cells and did not respond to the growth inhibitory effect of GAPDH." (PMID 25785838, 2015). "The HOTAIR expression levels of cancerous and adjacent noncancerous tissues from the gastric cancer patients were examined by qRT-PCR and normalized by the GAPDH expression level." (PMID 24130837, 2013). "However, GAPDH is considered to be necessary because a specific genetic marker for gastric cancer has not yet been found." (PMID 17667927, 2007). "However, the CM of gastric cancer cells did not affect GAPDH secretion from Hs738 cells." (PMID 25785838, 2015). "Thus, we applied non-parametric Mann-Whitney U-test for comparing non-normal distributed unmatched groups, and it showed significant differences in the expressions of GAPDH (p = 0.014) and B2M (p = 0.035) between 'stomach cancer cell lines' and 'non-stomach cancer cell lines'." (PMID 20507635, 2010). "To investigate the role of PVT1 in gastric cancer progression, we detected the PVT1 expression levels in 80 paired gastric cancer tissues and corresponding non-tumor tissues by using qRT-PCR, and normalizing to GAPDH." (PMID 25890171, 2015).
Sepsis (22 papers, 2012 to 2025). Sepsis is defined as life-threatening organ dysfunction caused by a dysregulated host response to infection. "In addition, the protective effect of glyceraldehyde-3-phosphate dehydrogenase (GAPDH) against sepsis-associated lung injury is mediated by enhanced ATG12-dependent autophagy." (PMID 36016930, 2022). "In addition, the protective effect of GAPDH (glyceraldehyde-3-phosphate dehydrogenase) against sepsis-associated lung injury is mediated by enhanced ATG12-dependent autophagy." (PMID 34164394, 2021). "Conversely the upregulated genes in sepsis Th1 cells showed enhanced endopeptidase activity (GAPDH; 0.75log2FC) and angiogenesis related (XBP1, CXCR4, and BTG1; 0.93, 0.66, and 0.64log2FC, respectively) pathways." (PMID 41208955, 2025). "Inflammatory conditions, including sepsis and autoimmune diseases, involve malonylation-driven regulation of immune responses, particularly through GAPDH-mediated cytokine translation." (PMID 41107644, 2025). "GAPDH expression was additionally assessed, as it has been reported to vary in elderly individuals with sepsis, yet frequently used to normalize gene expression in previous studies of neonates with sepsis." (PMID 38817614, 2024). "The administration of GAPDH exerts an anti-inflammatory effect by reducing tumor necrosis factor alpha (TNFα) levels in a mouse model of sepsis." (PMID 36818560, 2023). "In a sepsis model, 4-OI can improve the survival rate of septic mice by inhibiting GAPDH activity and reducing glycolysis, inhibiting the activation of inflammatory macrophages and the release of inflammatory cytokines." (PMID 36406124, 2022). "Induction of glycolysis leads to immunotolerant monocytes as seen in sepsis by their effects on posttranslational modification of effector molecules such as glyceraldehyde 3-phosphate dehydrogenase (GAPDH)." (PMID 33854499, 2021). "For instance, GAPDH has anti-inflammatory properties, preventing cytokine storm and mortality in a mouse model of LPS-induced sepsis." (PMID 34587193, 2021). "This is a phenomena recently noted in patients with sepsis, and brings into question the suitability of GAPDH as a reference gene when analyzing mRNA in cells from individuals with severe inflammation." (PMID 31403210, 2019). "For GAPDH, an apparent 1.4-fold higher mean abundance in sepsis than SIRS; however, passed the threshold of significance." (PMID 31075840, 2019). "In fact, treatment of LPS-induced sepsis mice with GAPDH lead to decrease inflammation and improve survival in a not fully understood mechanism suggesting that the regulation of GAPDH might be a tight point of control for the inflammatory response." (PMID 35154105, 2022). "Moreover, macrophage treated with 4-Octyl itaconate modulates GAPDH activity and glycolysis leading to a decrease in LPS-induced inflammation in vitro and in a sepsis model." (PMID 35154105, 2022). "GAPDH itself has been shown to have anti-inflammatory properties, as systemic administration of GAPDH prior to LPS-induced sepsis reduces cytokine storm and mortality, though the mechanism of this immunomodulatory effect remains unknown." (PMID 29213268, 2017). "GAPDH might also affect the inflammatory process through the regulation of tumor necrosis factor synthesis, with GAPDH-mediated proinflammatory cascades occurring after severe injury and sepsis." (PMID 36918848, 2023). "In sepsis RGS1, along with IRF4 and GAPDH, were highly upregulated across all B cell populations compared to control cells." (PMID 41208955, 2025). "In contrast, sepsis Treg cells displayed four upregulated genes (RGS1, HLA-DPA1, BTG1, and GAPDH; 1.25, 1.02, 0.44, and 0.43log2FC, respectively)." (PMID 41208955, 2025). "18S, GAPDH, and ACTB served as reference genes to compare sepsis and controls, 18S and GAPDH to compare elderly and young sepsis patients, and 18S to follow gene expression after LPS infusion." (PMID 31075840, 2019).
Sepsis (continued). "Together, these results challenge the suitability of 18S, GAPDH, and ACTB as reference genes in sepsis granulocytes." (PMID 31075840, 2019). "We speculated that GAPDH, MAPK8, PIK3CB, and MMP9 may play important roles in the ARDS-specific neutrophil phenotype distinct from sepsis." (PMID 31531373, 2019). "The importance of this mechanism is underscored by the finding that treating mice with recombinant GAPDH protein has an anti-inflammatory effect, reducing TNFα levels in a sepsis model (exogenous GAPDH likely sequesters TNFα mRNA without undergoing malonylation)." (PMID 41107644, 2025). "However, it is still not known whether, and in what way, the interrelationship between GAPDH and NLRP3 contributes to protection against pathogens or plays an important role in sepsis." (PMID 31403210, 2019).